GGT1 (gamma-glutamyltransferase 1)
Diseases named in the same sentence as GGT1 in open-access papers (continued):
Sharing a sentence is not in itself a finding about the gene and the disease.
pancreatitis (2 papers, 2024). Inflammation of the pancreas. "We investigated the expression of pancreatitis-associated genes with the ability to act as positive regulators of the IL-6 amplifier; these genes include GGT1, PRSS1, CASR, CTRB1, ABO, SPINK1, and CTRC." (PMID 38806529, 2024). "Finally, we did not investigate whether GGT1 SNP rs5751901 is involved in the development of pancreatitis in vivo." (PMID 38806529, 2024). "Instead, we employed a NF-κB-mediated dermatitis, because we did not have a model of pancreatitis, and we wished to investigate whether GGT1-mediated NF-κB activation plays a role in the development of inflammatory diseases in vivo via the IL-6 amplifier activation." (PMID 38806529, 2024).
schizophrenia (2 papers, 2020 to 2021). A major psychotic disorder characterized by abnormalities in the perception or expression of reality. "Given that the expression of both α and β subunits of GGT-1 are reduced, substrates of typical geranylgeranylation are likely to be the most impacted by altered prenylation in schizophrenia." (PMID 32123175, 2020).
alcohol abuse (1 paper, 2022). The use of alcoholic beverages to excess, either on individual occasions ("binge drinking") or as a regular practice. "Among the demonstrably active gene products, GGT1 is by far the best-characterized GGT protein and a prominent diagnostic serum marker, e.g., for liver damages, due to chronic hepatitis infections or long-term alcohol abuse." (PMID 35626629, 2022).
anaplastic astrocytoma (1 paper, 2021). "In detail, one patient collected tumor specimens in all stages of MT in the present cohort.PRKCQ,PPIF,NRP1,MEFV,GGT1,FAN1, andBTKmutations were found in both DA and anaplastic astrocytoma, whereas mutations ofTBC1D19,ESRRA,DIAPH2,COG6, andCBWD3occurred in HGA." (PMID 34430964, 2021).
apocrine breast carcinoma (1 paper, 2010). "The histological and immunohistochemical study showed that several cases had apocrine histological features and expressed GGT1, which is a potential new marker for apocrine breast carcinoma." (PMID 20712882, 2010).
apocrine carcinoma (1 paper, 2010). "In the new set of Cowden tumors, two have histological features of classic apocrine carcinoma (cases 295 and 891) and are GGT1 positive." (PMID 20712882, 2010). "Two are invasive ductal (cases 681 and 732), one is a micro papillary carcinoma (case 712), all with apocrine features that do not meet the full criteria for apocrine carcinoma; all three are weakly positive for GGT1." (PMID 20712882, 2010).
carcinoids (1 paper, 2016). "With respect to folic acid metabolism, carcinoids showed significantly higher expression than carcinomas for FOLR1 (p<0.0001), FPGS (p<0.0001) and GGT1 (p=0.0289)." (PMID 27064343, 2016).
cataract (1 paper, 2021). Partial or complete opacity of the crystalline lens of one or both eyes that decreases visual acuity and eventually results in blindness. "GGT1 knock-out mice showed chronic GSH deficiency, growth retardation, skeletal abnormalities and cataracts, and they died younger." (PMID 33917627, 2021).
chromophobe renal cell carcinoma (1 paper, 2025). Chromophobe renal cell carcinoma is a rare subtype of renal cell carcinoma, originating from the intercalating cells of the collecting ducts and macroscopically manifesting as a well-circumscribed, highly lobulated, solid tumor that is usually diagnosed at an early stage. "In chromophobe renal cell carcinoma (ChRCC), gamma-glutamyl transferase 1 (GGT1) expression is strikingly suppressed (nearly 100-fold lower than normal kidney), leading to markedly elevated intracellular glutathione (GSH) (GSH/GSSG) levels." (PMID 40836945, 2025).
diabetic retinopathy (1 paper, 2016). "Recently a common GGT1 gene variant in T2DM subjects was shown to have significant effects on a high baPWV and diabetic retinopathy with interaction with a low HDL-C level." (PMID 27491472, 2016).
dyslipidemia (1 paper, 2015). "In the general subjects, a significant interactive effect of the GGT1 genotype and dyslipidemia on the baPWV values was observed (P = 0.02)." (PMID 25952030, 2015).
fibroids (1 paper, 2025). "Within these 15 pairs, there were four unique genes (NQO1, AC004889.1, TXNL4B, and GGT1), and all four of those genes have not been previously associated with fibroids in the GWAS catalog and were significant only in the African ancestry analysis." (PMID 40050615, 2025).
follicular adenoma (1 paper, 2018). "Samples from the thyroiditis, follicular adenoma, Graves’ disease, and 3 adenomatous goiter cases including 1 mediastinal goiter case were judged negative by GGT1 immunohistochemical staining." (PMID 30479665, 2018).
glioblastoma (1 paper, 2024). The most malignant astrocytic tumor (WHO grade IV). "Notably, GGT1 decreases the susceptibility of glioblastoma cells to ferroptosis triggered by cystine deprivation, particularly under conditions of high cell density." (PMID 39624080, 2024). "Therefore, the combination of GGT1 inhibitors with ferroptosis inducers holds significant potential as a promising therapeutic strategy for glioblastoma." (PMID 39624080, 2024).
glioma (1 paper, 2024). A benign or malignant brain and spinal cord tumor that arises from glial cells (astrocytes, oligodendrocytes, ependymal cells). "We also explored the perturbation effects of these genes which suggested that the importance of DPEP1, G6PD, GGT1, GGT5, IDH1, and NFE2L2 for glioma cell survival." (PMID 38819225, 2024).
glutathionuria (1 paper, 2021). "Whole-genome sequencing identified a large homozygous intragenic deletion in GGT1 causing glutathionuria in the patients." (PMID 33916150, 2021).
Hypertension (1 paper, 2015). The presence of chronic increased pressure in the systemic arterial system. "According to the multiple regression models, age and hypertension were found to be independent risk factors for a high baPWV irrespective of the GGT1 genotype." (PMID 25952030, 2015).
liver disease (1 paper, 2024). "GWAS revealed an association between GGT1 and plasma levels of liver enzymes, as well as alcohol-associated liver disease." (PMID 38997780, 2024).
lymph node metastasis (1 paper, 2024). "Mutated genes associated with lymph node metastasis in the univariate analysis, including RET, ATM, PIK3CA, TERT, GGT1 and fusions, were incorporated to construct a gene signature model." (PMID 38886866, 2024).
myeloma (1 paper, 2022). "GGT1, ICAM3/CD50, and ICAM1/CD54, earlier identified in the myeloma cell line proteomics, were among the most enriched proteins on the primary myeloma cell surface relative to B-cells." (PMID 35840578, 2022). "Notably, we identified peptides from LILRB4, GGT1, and CCR10, further validating expression of surface markers on primary myeloma cells that we initially highlighted from cell line analysis." (PMID 35840578, 2022). "We were surprised to find the three proteins that most-distinguished myeloma plasma cells from B-ALL, based on fold-change and p-value, were not canonical markers at all: gamma-glutamyl transferase 1 (GGT1), selectin-P ligand (SELPLG), and cell adhesion molecule 1 (CADM1)." (PMID 35840578, 2022).
polycystic ovary syndrome (1 paper, 2024). A disorder that manifests as multiple cysts on the ovaries. "Previous studies have suggested that GGT1 and HNF1A genes may contribute to the abnormal glucose metabolism and altered lipid profile observed in Polycystic ovary syndrome, a significant clinical feature of the disorder." (PMID 38233749, 2024).
prostate tumors (1 paper, 2019). "In addition, seven other genes, GGT1, HDAC1, KLK2, MYO6, PLA2G7, BICD1, and CACNAID, were found to be differentially expressed in prostate tumors of non-BCR and BCR patients." (PMID 31741711, 2019).
renal carcinoma (1 paper, 2021). A carcinoma arising from the epithelium of the renal parenchyma or the renal pelvis. "Further, its inhibition significantly decreased the migration of tumor cells, suggesting that GGT1 might be of therapeutic interest for patients with renal cancer." (PMID 34513707, 2021). "Another study further revealed that serum exosomal GGT1 could be a useful marker for advanced clinical features of patients with renal cancer." (PMID 34513707, 2021).
Renal cyst (1 paper, 2024). A fluid filled sac in the kidney. "We found that multiple genes encoding enzymes in the γ-glutamyl cycle were highly downregulated in renal cysts, including γ-glutamyl transferase (GGT1, −14×), dipeptidase 1 (DPEP1, −32.5×), aminopeptidase N (ANPEP, −12×) and 5-oxoprolinase (OPLAH, −2.6×)." (PMID 39000280, 2024).
renal oncocytomas (1 paper, 2017). "All identified enzymes were basically unchanged, except gamma-glutamyl transpeptidase 1 and 5 (GGT1, 50-fold; GGT5, 15-fold), which were significantly down-regulated in renal oncocytomas." (PMID 29285300, 2017).
small cell carcinoma (1 paper, 2025). A neuroendocrine carcinoma composed of small malignant cells which are often said to resemble "oat cells" under the microscope. "Indeed, GGT1 expression levels were significantly lower in tumors with treatment-induced NEPC (t-NEPC) features and small cell carcinomas (SCC) compared to CRPC-adenocarcinomas (CRPC-Adeno)." (PMID 40094020, 2025).
Thiamine deficiency (1 paper, 2016). Thiamine deficiency is a condition that occurs due to not enough thiamine (vitamin B1). "The preceding results from GLAST deficient mice, hypoxia, ischemia, thiamine deficiency and carboplatin toxicity as well as our results for GGT1 deficient dwg/dwg mice suggest that oxidative stress is a common mechanism leading to IHC loss." (PMID 26977590, 2016).
thymoma (1 paper, 2023). A neoplasm arising from the epithelial cells of the thymus. "Nucleic acids were extracted from thymomas and normal tissues, and the expression level of GGT1 was evaluated by quantitative polymerase chain reaction (qPCR)." (PMID 36882498, 2023).
tumor (27 papers, 2015 to 2026). "Loss of Kindlin-1 leads to increased tumor growth, with many of the most upregulated genes in the Kindlin-1-depleted tumors linked to cancer prognosis, including Cstf2, Ppp1r10, Nr4a1 and Ggt1." (PMID 38982038, 2024). "IHC analysis of FH-deficient RCC showed that GGT1 was expressed in the tumor cells, whereas DPEP1 was primarily confined to the normal adjacent tissues." (PMID 37053010, 2023). "Expression of GGT1 was negatively correlated with tumor purity (r = −0.236, P = 9.03e-6) and positively associated with infiltration of CD4+ T cells (r = 0.148, P = 6.11e-3), macrophages (r = 0.163, P = 2.54e-3), and dendritic cells (r = 0.116, P = 3.25e-2)." (PMID 34513707, 2021). "Abnormal expression of GGT family proteins, including GGT1, could cause increased oxidative stress within tumor cells, which affects the TIME and influences the response to chemotherapeutic agents." (PMID 35387129, 2022). "In this regard, the thiol status of tumors aligns perfectly with enzyme abundances, as both GSH synthesis (e.g. GSS) as well as the extracellular GSH scavenging enzymes (GGT1/5) were prominently upregulated in tumor tissue." (PMID 40461450, 2025). "Previous studies have reported that GGT1 is involved in oxidative stress, ROS production, and tumor cell proliferation dense." (PMID 40836945, 2025). "We also showed that GGT1 expression was up-regulated in the tumor group relative to the matched adjacent samples." (PMID 38523299, 2024). "HLF transactivates gamma-glutamyltransferase 1 (GGT1), which promotes ferroptosis and cisplatin resistance, ultimately driving malignancy in tumor cells." (PMID 38533507, 2024). "In the cases that fluoresced, GGT1 was more highly expressed in tumor tissues than in normal tissues (Cases 1–3)." (PMID 36882498, 2023). "Subsequently, HLF promotes the ferroptosis resistance in TNBC cells via GGT1 and ultimately facilitates the malignant tumor progression." (PMID 34991659, 2022). "The involvement of GGT1 in drug resistance of cancer cells has been repeatedly reported in quite a number of different neoplasias (reviewed in 9)." (PMID 35669424, 2022). "In the primary tumor of Cases 1, 4 and 7, the expression patterns of GGT1 and CA9 were similar, while the expression patterns of GGT1 and CA9 were different in Cases 2, 3, 5, 6, and 8–12." (PMID 30542087, 2018). "The inside of mLN exhibited central necrosis, and expression of CA9 and GGT1 was higher than that in the primary tumor, despite the small size of the mLNs, suggesting that blood supply did not depend on size." (PMID 30542087, 2018). "Blocking the GGT1 signaling pathway activates phagocytosis and promotes tumor eradication." (PMID 40836945, 2025). "Tumor-associated macrophages can secrete transforming growth factor beta (TGF-β) to turn on hepatic leukemia factor (HLF), which enhances the transcription of gamma-glutamyltransferase 1 (GGT1) and promotes resistance to ferroptosis in TNBC." (PMID 39833180, 2025). "Additionally, IF examination of tumor sections from both lung tissues and primary tumor tissues indicated GGT1 depletion accompanied by low level of CD44." (PMID 38523299, 2024). "Single agent of GGT1 inhibitor has the ability to inhibit the RASmut tumor cells, and inhibition of both FT and GGT1 markedly reduced RAS‐driven tumor growth and completely inhibit the prenylation in the preclinical setting." (PMID 41492362, 2026). "TGF-β1, in turn, promotes HLF to activate gamma-glutamyl transferase 1 (GGT1), which promotes drug resistance in tumor cells and TNBC cell proliferation and metastasis by promoting ferroptosis." (PMID 39273650, 2024). "In TNBC, hepatic leukemia factor (HLF) transactivated gamma-glutamyltransferase 1 (GGT1) promote the ferroptosis resistance and interactive dialogue between TNBC cells, and TAMs promotes sustained activation of HLF in tumor cells through the IL-6–TGF-β1 axis." (PMID 37681908, 2023).
tumor (continued). "Based on these results, we performed immunohistochemistry of GGT1 and CA9 for primary tumor and mLNs of the mouse model." (PMID 30542087, 2018). "GGT1, a member of the GGT family, has been shown to inhibit ferroptosis via the GSH/GPX4 axis and thus inhibit tumour progression 6, 29, and its amino acid sequence shares 34% homology with its fellow family member GGT7, the protein space structure also has similarity." (PMID 38911386, 2024). "Researchers have demonstrated that granulocyte colony-stimulating factor (G-CSF) upregulates GGT1 and enhances the immunosuppressive function of myeloid-derived suppressor cells, and GGT inhibitors can alleviate tumor immunosuppression and the tumor-promoting effect of G-CSF." (PMID 36761721, 2023). "On the other hand, in the case that did not fluoresce, GGT1 was rarely observed in either normal or tumor tissue (Case 4)." (PMID 36882498, 2023). "GGT1 and CA9 were expressed inside the primary tumor and in mLNs." (PMID 30542087, 2018). "The cluster of upregulated genes contained those mainly involved in metabolism such as GGT1 (gamma glutamyl transferase 1), vesicular traffic/secretion such as SYT13 (synaptotagmin XIII) and tumor suppression such as ARMCX3 (armadillo repeat-containing X-linked protein 3) and ARMCX6." (PMID 30337535, 2018). "However, the relationship between GGT1, GGTLC1, and the IME of KIRC and the mechanisms leading to tumor heterogeneity have not been fully investigated." (PMID 40836945, 2025).
cancer (26 papers, 2014 to 2026). A tumor composed of atypical neoplastic, often pleomorphic cells that invade other tissues. "The mutation frequencies in BRAF, TERT, RET, ATM and GGT1 were significantly higher in cancer tissues than benign nodules." (PMID 38886866, 2024). "GGT1 expression has been associated with a subset of basal cancers and our data indicating elevated levels of gamma-glutamyl amino acids in ER- cancers provides functional support for this genetic link." (PMID 25091696, 2014). "Furthermore, the mutation frequencies of DNA damage repair genes ATM and metabolism-associated genes GGT1 were significantly higher in cancer tissues than benign nodules." (PMID 38886866, 2024). "Recently, GGT1 was implicated in the progression and metastasis of several cancers." (PMID 34513707, 2021). "Research indicates that the expression levels of general stem cell markers (such as CD34 and CD73), genes linked to cancer stem cells (CD99 and ITGB3), and an embryonic stem cell marker (GGT1) are elevated within this subset." (PMID 41204265, 2025). "Since the results were obtained from the cell cultivation alone, an in vivo study would be required if this regulation of ferroptosis by GGT1 is to be considered a target of cancer treatment." (PMID 37175751, 2023). "Intriguingly, similar renal metabolic rewiring was observed in benign and malignant tumors derived from the impairment of mitochondrial complex 1 or GGT1 in human kidneys." (PMID 34492635, 2021). "Considering the biological relevance of GGT1 in other cancer types, the activity of exosomal GGT1 was assessed in more detail in serum (n = 31 PC and n = 8 BPH)." (PMID 30158500, 2018). "Some cases expressed GGT1 in cancer cells, and others expressed GGT1 not only in cancer cells, but also in the interstitial spaces around them." (PMID 30542087, 2018). "Since serum GGT activity is reported to be elevated in patients with certain types of cancer, we focused on GGT1 as a potential exosomal marker for PC in the subsequent studies." (PMID 28476099, 2017). "The negativity of the two cancer cases for GGT1 antibody might be attributable to the low specificity of the GGT antibody to the GGT1 antigen." (PMID 30479665, 2018). "Serum exosomal GGT activity could be a useful marker to diagnose PC or to distinguish PC from BPH and possibly to diagnose other types of cancer with increased GGT1 expression." (PMID 28476099, 2017). "This may suggest that GGT1 was derived from both cancer cells and stromal cells." (PMID 30542087, 2018). "Our results showed that prostate tissues expressed four major isoforms of GGT family genes (GGT1/5/6/7), of which GGT1 expression was upregulated but GGT6/GGT7 expression was downregulated in cancer tissues compared to benign tissues." (PMID 40094020, 2025). "The GGT1/5/7 and GGT‐II isoforms represent promising biomarkers for early diagnosis, prognosis, and therapeutic targeting in multiple cancers." (PMID 41316810, 2025). "Compared to case-matched benign tissues, most cases of cancer tissues expressed higher GGT1/GGT5 genes but lower GGT6/GGT7 genes, of which GGT6 expression showed a dramatic reduction in cancer tissues." (PMID 40094020, 2025). "Since it has been proved that GGT1 as a member of GGT family was involved in drug resistance, but role of GGT5 during cancer chemotherapy is unclear." (PMID 32640421, 2020). "In PC tissues, cancer cells showed cytoplasmic and membranous expression for GGT1 and background noncancerous prostatic glands showed weak apical expression." (PMID 28476099, 2017). "Furthermore, cancer cells showed stronger expression for GGT1 in the cytoplasm and membrane than background noncancerous prostatic glands." (PMID 28476099, 2017). "However, GGT1 methylation had no significant alteration and GGT5 methylation was significantly elevated in cancer tissues, which is not in line with the upregulation of GGT5 expression in cancer tissues." (PMID 40094020, 2025).
cardiovascular diseases (3 papers, 2020 to 2025). "The identification of GGT1 as a key mediator positions Sal as a promising candidate for clinical translation in cardiovascular diseases." (PMID 40438595, 2025).